NRAS (NRAS proto-oncogene, GTPase)
Diseases named in the same sentence as NRAS in open-access papers (continued):
Sharing a sentence is not in itself a finding about the gene and the disease.
ameloblastoma (8 papers, 2017 to 2025). The most common odontogenic tumor, arising from the epithelial component of the embryonic tooth and usually affecting the molar-ramus region of the mandible or maxilla. "Considering NRAS, a recent paper by Oh and Hong identified the NRAS G12D mutation in a case of peripheral ameloblastoma arising in the mandibular alveolar mucosa of a 65-year-old man." (PMID 39597858, 2024). "In contrast, BRAF or NRAS mutations were observed in 12 and two control samples of ameloblastoma, respectively." (PMID 28658279, 2017). "Thus, next-generation and direct sequencing collectively indicate that all 14 ameloblastomas harbor either BRAF Val600Glu or NRAS Gln61Arg mutations." (PMID 28658279, 2017). "At the molecular level, mutations in the mitogen-activated protein kinase (MAPK) pathway, including BRAF V600E, FGFR2, and NRAS, have been identified in ameloblastomas, including PA." (PMID 41030734, 2025). "In a similar way, other somatic mutations have been reported in ameloblastoma, mainly affecting: SMO, other MAPK pathway-related genes such as KRAS, NRAS, HRAS, FGFR2 and in a lower frequency, PTEN and CTNNB1 among others." (PMID 35048068, 2021). "Mutually exclusive and less common mutations affecting other MAPK-related genes, such as KRAS, NRAS, HRAS, and FGFR2 (a receptor whose stimulation activates MAPK/ERK pathway) have been reported in BRAF wild-type ameloblastomas." (PMID 35048058, 2021). "Remarkably, the unilocular to multilocular pattern rate was higher (1.3:1, 1.5:1, respectively) in the tumors with BRAF and multiple gene mutations, in contrast to SMO, NRAS, HRAS, and EGFR-mutated ameloblastomas (1:3, 1:2, respectively)." (PMID 29388014, 2018). "In ameloblastoma samples, a Val600Glu mutation in BRAF was found in 5 of 7 cases, and a Gln61Arg mutation in NRAS was found in the other two cases." (PMID 28658279, 2017). "Additionally, single somatic mutations in NRAS and SMO have also been detected in one peripheral ameloblastoma sample each in a mutually exclusive manner with the BRAF mutation." (PMID 35048058, 2021). "However, other Authors showed additional mutations to B-Raf in ameloblastomas, such as NRAS, HRAS, KRAS, FGFR2, and PIK3CA,10,23,44 suggesting they may represent secondary mutations occurring later in the pathogenesis of ameloblastoma." (PMID 35468886, 2022). "In ameloblastoma without BRAF Val600Glu, we found NRAS Gln61Arg, which is in agreement with a previous report showing that RAS mutations (including NRAS Gln61Arg) and BRAF Val600Glu are mutually exclusive." (PMID 28658279, 2017).
CNS melanoma (8 papers, 2014 to 2025). "A case series described four patients with NRAS‐mutant CNS melanoma associated with CMN and neurologic abnormalities who were treated with trametinib." (PMID 41141235, 2025). "Trametinib is the first therapy to show any objective or measurable effect in NRAS-mutated primary CNS melanoma, with few side effects in this small series." (PMID 28253523, 2017). "In addition to imaging, pathology plays a crucial role as a diagnostic tool, with markers like Melan A and HMB-45, along with the NRAS mutation, being the predominant markers identified in primary central nervous system melanoma." (PMID 40417324, 2025). "Four children with NRAS-mutated CNS melanoma were treated with Trametinib on a compassionate basis." (PMID 28253523, 2017). "The authors reported 2 cases of children with melanoma of the CNS that presented mutations in the NRAS gene, and highlighted that melanoma of the CNS is associated with mutations in the GNAQ and GNA11 genes, whereas mutations in the NRAS gene are rare in adults." (PMID 26622814, 2015). "In addition, we previously reported on a mouse model in which embryonic induction of oncogenic NRAS mutation led to NCM-like disease in mice with development of primary CNS melanoma." (PMID 24713450, 2014). "Trametinib (MEK inhibition) is the first medical therapy to have had any observable effect in primary NRAS-driven CNS melanoma in children in our cohort." (PMID 28253523, 2017). "Thus far, all primary childhood melanomas of the CNS and leptomeningeal melanocytosis were found to harbor somatic NRAS mutations: in the 6 cases reported in literature, including the present case, a codon 61 mutation in NRAS was demonstrated (1 case Q61L, 3 cases Q61R, 2 cases Q61K)." (PMID 24713450, 2014).
metastasis (8 papers, 2018 to 2025). The spread or migration of cancer cells from one part of the body (where they first appeared) to another. "Among these, NSCLC patients with BRAF mutations had more pleural metastasis (47.1% vs.16.8%, P = 0.005), and NRAS mutations had lung (60.0% vs.12.4%, P = 0.025) and pleural metastasis (60.0% vs.16.8%, P = 0.038)." (PMID 39464712, 2024). "Lung metastasis (3 cases, 60.0%, P = 0.017) and plural metastasis (3 cases, 60.0%, P = 0.038) frequently occurred in the NRAS mutation group." (PMID 39464712, 2024).
mucinous adenocarcinoma (8 papers, 2019 to 2026). An invasive adenocarcinoma composed of malignant glandular cells which contain intracytoplasmic mucin. "High ACE2 exhibited significant associations with nerve invasion, lower expression in mucinous adenocarcinomas, and NRAS (Q61R/L/H/K) mutations." (PMID 41488286, 2026). "Mucinous adenocarcinoma was more common in tumors with BRAF/NRAS mutations than in KRAS mutant or WT tumors." (PMID 41439081, 2025). "Key findings include a high frequency of KRAS mutations, a trend linking BRAF/NRAS mutations to mucinous adenocarcinoma, and a significant association between KRAS mutations and older patient age." (PMID 41439081, 2025). "Mucinous adenocarcinoma was more common in tumors with BRAF/NRAS mutations (two of six cases, 33.3%) compared with KRAS-mutated tumors (six of 39 cases, 15.4%) or WT tumors (two of 27 cases, 7.4%)." (PMID 41439081, 2025). "Mucinous adenocarcinoma occurred more than twice as frequently in BRAF/NRAS-mutated tumors as in KRAS-mutated tumors, and more than four times as frequently as in WT tumors." (PMID 41439081, 2025). "NRAS MAF level was significantly higher in patients with mucinous adenocarcinoma and for those with lung metastases." (PMID 37296579, 2023). "In contrast, another study found an association between mucinous adenocarcinoma and KRAS mutations, but not with NRAS or BRAF mutations." (PMID 35681771, 2022). "Another study found an association between mucinous adenocarcinoma and KRAS mutations, but not with NRAS or BRAF mutations." (PMID 35681771, 2022). "Significantly higher KRAS MAF levels were detected in patients with G2 tumor grading, liver metastasis, and in those who did not undergo surgery at site of primary tumor; as for NRAS, significantly higher levels were found in patients with mucinous adenocarcinoma or with lung metastasis." (PMID 37296579, 2023).
rhabdomyosarcoma (8 papers, 2014 to 2025). A rare aggressive malignant mesenchymal neoplasm arising from skeletal muscle. "Oncogenic mutant NRAS protected cells from oxidative stress-induced ferroptosis in primary rhabdomyosarcoma, whereas wild-type NRAS appeared to do the opposite." (PMID 36386203, 2022). "Knockdown of HGMA2 in embryonic rhabdomyosarcoma cells resulted in severe downregulation of IGF2BP2 and knockdown of either HGMA2 or IGF2BP2 led to reduced protein levels encoded by the neuroblastoma RAS viral (v-ras) oncogene homolog (NRAS)." (PMID 25923053, 2015).
serous ovarian carcinomas (8 papers, 2017 to 2026). "The primary aim of this study was to verify if a fully integrated, real-time PCR-based Idylla system can be used for the rapid determination of the NRAS mutation status in patients with serous borderline ovarian tumors and low-grade serous ovarian carcinomas." (PMID 29682098, 2018). "NRAS mutation in codon 13 (G13D, p.Gly13Asp; nucleotide: c.38G>A) was found in one patient, a woman with low-grade serous ovarian carcinoma." (PMID 29682098, 2018). "The primary aim of this study was to verify if a fully integrated, real-time PCR-based Idylla system can be used for the rapid determination of NRAS mutation status in patients with serous borderline ovarian tumors and low-grade serous ovarian carcinomas." (PMID 29682098, 2018). "NRAS mutation in codon 13 (G13D, p.Gly13Asp; nucleotide: c.38G>A) was found in one patient (8.3%), a woman with low-grade serous ovarian carcinoma." (PMID 29682098, 2018). "NRAS mutation (e.g., Q61K) has also been identified in low-grade serous ovarian cancer." (PMID 36430761, 2022). "Significant co-occurrence of mutations in NRAS and EIF1AX was also found in low-grade serous ovarian carcinomas." (PMID 36589683, 2022). "Typically, low-grade serous ovarian carcinoma has few somatic mutations, which are mainly found in genes associated with the mitogen-activated protein kinase pathway such as KRAS, BRAF and NRAS." (PMID 29132324, 2017). "Dariush and colleagues demonstrated that NRAS, an oncogenic driver in serous ovarian carcinomas, could co-expressed with EIF1AX, which promoted clonogenicity and proliferation in OV." (PMID 37730669, 2023).
anaplastic thyroid carcinoma (7 papers, 2019 to 2025). "Patient 19, anaplastic thyroid carcinoma with an NRAS mutation, had spontaneous shrinkage of the tumour." (PMID 35606463, 2022). "Anaplastic thyroid carcinoma, BRAF non-V600, NRAS, combination immunotherapy and targeted therapy, case report." (PMID 37122752, 2023).
chronic myeloid leukemia (7 papers, 2015 to 2025).
fibrosarcoma (7 papers, 1993 to 2025). A malignant mesenchymal fibroblastic neoplasm affecting the soft tissue and bone. "The HT-1080 cell line used in this study is a fibrosarcoma cell line, bearing an NRAS mutation, and also expressing high levels of MMP-9, which contributes to its invasiveness." (PMID 39519810, 2024).
leukocytosis (7 papers, 2017 to 2025). "Clinically, CBL mutations were associated with increased bone marrow blasts at diagnosis, leukocytosis and splenomegaly, similar to patients harboring NRAS or KRAS mutations." (PMID 39298477, 2024). "Notably, NRAS mutation was correlated with leukocytosis (p < 0.05)." (PMID 35610628, 2022). "In addition, in the combined WES cohort, NRAS mutations were most significantly associated with aggressive disease features, such as leukocytosis (OR = 3.0, CI: 1.7–5.1) and LT risk (OR = 2.7, CI: 1.4–5.3), with the number of driver mutations correlating with disease severity in CMML." (PMID 34006870, 2021). "Clinically, CBL mutations were associated with a more proliferative phenotype evidenced by increased bone marrow blasts, leukocytosis and splenomegaly, similar to other RAS pathway mutations such as KRAS, NRAS and PTPN11." (PMID 39298477, 2024). "In contrast, mice expressing both NRAS(G12D) and TCF7-SPI1 presented with leukocytosis and splenomegaly but no enlarged thymus." (PMID 34230493, 2021).
osteosarcoma (7 papers, 2020 to 2023). A usually aggressive malignant bone-forming mesenchymal neoplasm, predominantly affecting adolescents and young adults. "In osteosarcoma, NRAS was reported to be associated with cell proliferation, migration, invasion, and methotrexate resistance." (PMID 33193737, 2020). "Therefore, miR-148a-3p in extracellular vesicles may regulate the metastatic potential of osteosarcoma cell lines by potentially inhibiting a network of genes that includes NRAS." (PMID 36349193, 2022). "Genes involved in epithelial cell proliferation, such as BCL11B, NRAS, THBS1, and VEGFC, promote angiogenesis and tumorigenesis, reflecting the heterogeneity of osteosarcoma-related genes." (PMID 35610231, 2022).
brain tumor (6 papers, 2014 to 2025). "DNA sequencing showed shared mutations in codon 13 of NRAS in the melanocytic nevi and the brain tumor." (PMID 25330907, 2014). "Another model of NRAS activation in embryonic OPCs generated malignant brain tumors in zebrafish, which captured the oligodendroglial profile similar to NB-FOXR2 but lacked a neuronal component." (PMID 39495206, 2025). "The patient’s resected brain tumor is BRAF V600E mutated, NRAS wild type (WT), and TERT C250T mutated." (PMID 26597176, 2015). "CNV events affecting these three likely pathogenic mutations, GNAQ R183Q, S1PR3 G89S, and NRAS G12V, were observed exclusively in abdominal and brain tumor samples and not detected in the cerebral cortex, white matter, or skin." (PMID 38254245, 2024). "Together, these results demonstrate the zebrafish rb1 brain tumors have a highly proliferative, poorly differentiated state with an oligoneural precursor molecular signature found in human OLIG2+/SOX10+ and zebrafish NRAS CNS-PNETs." (PMID 29914980, 2018).
cervical cancer (6 papers, 2015 to 2024). A primary or metastatic malignant neoplasm involving the cervix. "The expression of seven hub genes in the PI3K/AKT/mTOR pathway were increased in cervical cancer: EIF4EBP1, GSK3B, HRAS, KRAS, NRAS, PIK3CB and PIK3R2." (PMID 36911370, 2023).
colon adenocarcinoma (6 papers, 2015 to 2021).
esophageal cancer (6 papers, 2017 to 2025). A primary or metastatic malignant neoplasm involving the esophagus. "However, KRAS and NRAS mutations are rarely observed in esophageal cancer." (PMID 28038457, 2017). "Among these genes, MAP2K4 and NRAS are reported as driver genes by IntOGen, while NTRK3 is listed as a driver gene for esophageal cancer and stomach adenocarcinoma." (PMID 39554798, 2024).
pancreatic ductal adenocarcinoma (6 papers, 2020 to 2025). An infiltrating adenocarcinoma that arises from the epithelial cells of the pancreas. "The RAS family of oncoproteins (KRAS, HRAS, and NRAS) drive aggressive cancers like pancreatic ductal adenocarcinoma (PDAC) and non-small cell lung cancer (NSCLC), yet targeting mutant RAS has historically been challenging due to its “undruggable” structure." (PMID 41471277, 2025). "In pancreatic ductal adenocarcinoma, KRAS mutations dominate (~90–95%), especially at codon 12 (G12D, G12V, G12R), while NRAS and HRAS mutations are essentially absent." (PMID 41515890, 2025).
Pleural effusion (6 papers, 2019 to 2022). The presence of an excessive amount of fluid in the pleural cavity. "NRAS c.182A > G mutation was detected at a low frequency in cfDNA isolated from plasma and pleural effusion using ddPCR." (PMID 31511039, 2019). "We performed whole-exome sequencing of DNA samples from leukocytes and a biopsy specimen and analyzed cell-free DNA (cfDNA) from plasma and pleural effusion of patients to identify the NRAS c.182A > G (p.Q61R) mutation using the droplet digital polymerase chain reaction (ddPCR)." (PMID 31511039, 2019). "Detection of BRAF p.V600E (VAF of 49%), NRAS p.Q61K (VAF of 19%) and NRAS p.Q61 (VAF of 3.3%) in this pleural effusion specimen are consistent with two NRAS-mutated resistant subclones emerging following targeted therapy." (PMID 31277584, 2019).
serous carcinomas (6 papers, 2015 to 2024). "As patient EOC754 exhibited an NRAS mutation and an atypical copy number profile resembling the low-grade serous carcinomas of patients EOC545 and EOC466, a gynecological pathologist performed a retrospective histological review of her archival tumor samples." (PMID 39101783, 2024). "So, we wanted to evaluate the clinical benefit of MEK inhibitors in the management of advanced-stage low-grade serous carcinoma harboring KRAS or NRAS mutation." (PMID 35328764, 2022).
viral infection (6 papers, 2014 to 2025). "Some cases have been linked to viral infections, including Epstein–Barr virus, cytomegalovirus, human herpesviruses, and human immunodeficiency virus, as well as somatic mutations in genes such as NRAS, KRAS, MAP2K1 and ARAF." (PMID 41321345, 2025). "Thus, both LCH and pulmonary LCH harbor the BRAF V600E mutation and NRAS mutation and appear related to external stimuli such as viral infection and cigarette smoking." (PMID 30134914, 2018). "However, recent data indicate both LCH and pulmonary LCH harbor the BRAF V600E and NRAS mutation and appear linked to external stimuli such as viral infection and cigarette smoking." (PMID 30134914, 2018). "By contrast, neither mutations in BRAF or NRAS nor an involvement of viral infection were found." (PMID 24535703, 2014).
congenital melanocytic nevi (5 papers, 2021 to 2025). "NRAS is an oncogene contributing to the development of congenital melanocytic nevi, a condition associated with HC." (PMID 38439105, 2024). "The second was the description of pigmentary and vascular abnormalities in individuals with an entirely distinct mosaic disorder congenital melanocytic nevus syndrome caused by NRAS or BRAF mosaic variants." (PMID 36566878, 2023). "Moreover, the pathogenic variants in NRAS and BRAF were also identified in the other melanocytic neoplasms, including congenital melanocytic nevi." (PMID 34643354, 2021).
embryonal rhabdomyosarcoma (5 papers, 2018 to 2025). A poorly circumscribed morphologic variant of rhabdomyosarcoma. "The two main subtypes are alveolar rhabdomyosarcoma (ARMS), which is associated with PAX3/7-FOXO1 fusion genes, and embryonal rhabdomyosarcoma (ERMS), which is associated with mutations in common cancer genes such as HRAS, KRAS, NRAS, CTNNB1, PIK3CA and TP531." (PMID 30353028, 2018). "In cancers such as embryonic rhabdomyosarcoma (ERMS), HMGA2 upregulates IMP2, stabilizing NRAS mRNA and sustaining oncogenic NRAS signaling." (PMID 40141058, 2025). "In the Ptch+/- mouse model for embryonal rhabdomyosarcoma (ERMS), we recently showed that oncogenic (onc) H-, K- or NRAS mutations do not influence tumor growth when induced at the advanced, full-blown tumor stage." (PMID 34948179, 2021).
Lynch syndrome (5 papers, 2016 to 2024). An autosomal dominant hereditary neoplastic syndrome characterized by the development of colorectal carcinoma and a high risk of developing endometrial carcinoma, gastric carcinoma, ovarian carcinoma, renal pelvis carcinoma, and small intestinal carcinoma. "Since biomarker testing was mostly relevant for patients considered for anti-EGFR therapy (KRAS, NRAS) or younger patients (MMR testing for Lynch syndrome or BRAF testing for prognostication), it is possible that more young and fit patients with mCRC were tested." (PMID 37071802, 2023). "Unfortunately, data on sporadic mismatch repair deficiency, germeline-mutation prompted Lynch Syndrom, BRAF/KRAS/NRAS mutations, or any family history can not be ascertained from the SEER data." (PMID 27464835, 2016).